XRCC1 (X-ray repair cross complementing 1)
Diseases named in the same sentence as XRCC1 in open-access papers (continued):
Sharing a sentence is not in itself a finding about the gene and the disease.
non-small cell lung carcinoma (27 papers, 2005 to 2025). A group of at least three distinct histological types of lung cancer, including non-small cell squamous cell carcinoma, adenocarcinoma, and large cell carcinoma. "Based on the conducted research, with the limitation of the low sample size, it can be assumed that the single nucleotide polymorphism Arg399Gln of the XRCC1 gene has limited prognostic significance in non-small cell lung cancer and requires further studies." (PMID 40650316, 2025). "Studies suggest that the Arg399Gln polymorphism of the XRCC1 gene has limited prognostic significance in non-small cell lung cancer." (PMID 40650316, 2025). "The aim of this study is to determine the prognostic significance of the single nucleotide polymorphism Arg399Gln of the XRCC1 gene in patients with non-small cell lung cancer." (PMID 40650316, 2025). "The study analyzed the importance of single nucleotide polymorphisms of the Arg399Gln gene of the XRCC1 gene in patients with non-small cell lung cancer." (PMID 40650316, 2025). "Radiotherapy has been reported to be more effective in patients with non-small cell lung cancer who have XRCC1 gene mutations." (PMID 38217545, 2024). "A more recent meta-analysis including 23 studies (n = 5567) of Asian patients with non-small-cell lung cancer, showed that rs25487 variant of the XRCC1 gene is a potential marker to predict clinical outcomes of platinum-based chemotherapy in Asian patients." (PMID 38789983, 2024). "Polymorphisms in XRCC1 and folate metabolism genes can affect the prognosis of patients with non-small cell lung cancer." (PMID 37679817, 2023). "Other studies have shown association of XRCC1 with survival and/or risk in non-small-cell lung cancer, colorectal and laryngeal squamous cell cancer." (PMID 35996502, 2022). "Resveratrol has been shown to inhibit the expression of XRCC1 and increase the etoposide-associated apoptosis in non-small cell lung cancer (NSCLC) cells." (PMID 36180892, 2022). "Some studies have shown that XRCC1 Arg399Gln is significantly associated with the prognosis of non-small cell lung cancer." (PMID 33327321, 2020). "Nevertheless, one study did show that a novel polymorphism in XRCC1 gene reduced its promoter activity, thus leading to lower protein levels and increased risk of non-small cell lung cancer." (PMID 25800737, 2015). "Studies addressing the association of XRCC1 gene polymorphisms at codon 194 with chemotherapy response have focused mainly on non-small cell lung cancer." (PMID 19563645, 2009). "Several polymorphisms have been identified in the XRCC1 gene that may play an important role in the development of non-small cell lung cancer." (PMID 40650316, 2025). "Carriership of variant allele of the XRCC1 Arg194Trp polymorphism may indicate better response to treatment with platinum derivatives in patients with advanced non-small-cell lung cancer." (PMID 26019482, 2014). "Carriership of the 312Asn allele in the XPD gene and the 399Gln allele in the XRCC1 may be associated with shorter survival in patients with non-small-cell lung cancer treated with platinum agents." (PMID 26019482, 2014). "Given that the predictive value of XRCC1 polymorphisms on platinum-based chemotherapy in non-small cell lung cancer has already been validated, such as XRCC1 Arg194Trp, it is reasonable to conclude that Arg194Trp may play a similar role in bladder cancer." (PMID 23704969, 2013). "In this context, overall survival was longer in Asians than Caucasians for non-small-cell lung cancer patients carrying XRCC1 rs25487 treated with chemotherapy, including platinum-based drugs." (PMID 36497451, 2022).
non-small cell lung carcinoma (continued). "In addition, an abundant level of XRCC1 transcription has been reported to decrease the cytotoxicity of cisplatin in non-small cell lung cancer." (PMID 29117108, 2017). "However, Forest plot showed a behaviour as toxic agent of mut/het XRCC1 Arg399Gln in agreement with an increased rate of lung effects in non small cell lung cancer patients." (PMID 22272830, 2012). "Interestingly, it has been recently described that XRCC1 transcript abundance levels correlate with cisplatin chemoresistance in non-small cell lung cancer cell lines." (PMID 18793406, 2008). "It has been reported that XRCC1 expression induced by etoposide treatment was dependent on ERK and Akt activation in non-small-cell lung cancer cells." (PMID 29117108, 2017).
bladder cancer (18 papers, 2007 to 2021). "Our study is the first report showing that XRCC1 gene rs3213356 and rs25487 CT genotype decreased the risk of bladder cancer, whereas XRCC1 rs3213356 CC and rs1799782 AA genotypes increased the risk of the disease in Chinese population." (PMID 27153553, 2016). "In XRCC1 rs3213356, compared to TT genotype, CT genotype showed a decreased risk while CC genotype showed an increased risk of bladder cancer (P = 0.002, adjusted OR = 0.43, 95% CI: 0.25–0.74; P = 0.005, adjusted OR = 5.76, 95% CI: 1.69–19.67, respectively)." (PMID 27153553, 2016). "Recently, several meta-analyses reported significant associations between polymorphisms of XRCC1 Arg194Trp, Arg280His, and Arg399Gln and bladder cancer." (PMID 25938407, 2015). "We conducted a meta-analysis to ascertain the association of XRCC1 Arg194Trp, Arg280His and Arg399Gln polymorphisms with bladder cancer risk in Asian population." (PMID 23704969, 2013). "Despite these limitations, this meta-analysis suggests that XRCC1 R194W and R280H polymorphisms were both associated with increased bladder cancer risk among Asians." (PMID 24039945, 2013). "Our meta-analysis shows that XRCC1 Arg194Trp and Arg280His polymorphisms are associated with a significantly increased risk of bladder cancer in Asian population." (PMID 23704969, 2013). "Twenty studies were included in this meta-analysis on the associations of the XRCC1 genetic polymorphisms with the risk of bladder cancer." (PMID 23496911, 2013). "Different from previous meta-analyses, we found that XRCC1 Arg194Trp and Arg280His polymorphisms significantly increased bladder cancer risk in Asian population." (PMID 23704969, 2013). "The XRCC1 Arg194Trp polymorphism was associated with an increased risk for bladder cancer in all subjects (OR = 1.69, 95% CI = 1.25 to 2.28, P = 0.001)." (PMID 23496911, 2013). "The present study is the first meta-analysis aimed to ascertain the correlation between XRCC1 polymorphisms (Arg194Trp, Arg280His, and Arg399Gln) and susceptibility to bladder cancer in Asian population." (PMID 23704969, 2013). "Currently there are limited studies on XRCC1 R194W and R280H polymorphisms and bladder cancer risk among Asian populations and African populations." (PMID 24039945, 2013). "Well-designed studies with large sample size are warranted to determine the role of XRCC1 polymorphisms in bladder cancer, especially for Arg194Trp and Arg280His." (PMID 23704969, 2013). "A lot of studies have investigated the correlation between x-ray cross complementing group 1 (XRCC1) polymorphisms and bladder cancer risk, but the results in Asian population were still inconclusive." (PMID 23704969, 2013). "Crude odds ratios with 95% confidence intervals were used to assess the associations between XRCC1 Arg194Trp and Arg399Gln polymorphisms and bladder cancer risk." (PMID 23496911, 2013). "This meta-analysis indicated that XRCC1 R399Q polymorphism was associated with decreased bladder cancer risk among smokers under the recessive genetic model and the homozygote contrast." (PMID 24039945, 2013). "This is the first meta-analysis conducted in Asian investigating the correlation between XRCC1 polymorphisms and susceptibility to bladder cancer." (PMID 23704969, 2013). "Numerous genetic association studies have investigated the correlation between XRCC1 polymorphisms and bladder cancer risk; however, the results were inconclusive or even contradictory." (PMID 23704969, 2013). "The Arg194Trp and Arg399Gln polymorphisms are the most well characterized XRCC1 polymorphisms, but the reported associations with bladder cancer risk among studies are inconsistent." (PMID 23496911, 2013). "We found that the XRCC1 R399Q polymorphism was associated with a decreased bladder cancer risk among smokers (AA vs. GG: OR=0.693, 95%CI= 0.515-0.932, P=0.015 and recessive model AA vs. GA+GG: OR=0.680, 95%CI= 0.515-0.898, P=0.007, respectively)." (PMID 24039945, 2013).
bladder cancer (continued). "Many previous studies have been conducted to evaluate the associations of XRCC1 polymorphisms with bladder cancer risk." (PMID 23496911, 2013). "In the present study, we performed a comprehensive analysis of 14 potentially functional polymorphisms (coding and non coding) in XRCC1 to investigate their associations with bladder cancer." (PMID 17425776, 2007). "A few other studies have investigated interactions between XRCC1 polymorphisms and smoking on bladder cancer risk." (PMID 17425776, 2007). "The association between XRCC1 Arg280His and an increased risk of bladder cancer is biologically plausible." (PMID 17425776, 2007). "Similarly, lower expression levels of XRCC1 in bladder cancer tumour cells were associated with worse survival after radiotherapy." (PMID 25800737, 2015). "This meta-analysis suggests that the XRCC1 R399Q polymorphism may play a protective role against bladder cancer among smokers." (PMID 24039945, 2013). "The meta-analysis results suggest that XRCC1 Arg194Trp and Arg399Gln polymorphisms may be associated with elevated bladder cancer risk." (PMID 23496911, 2013). "Meta-analysis results of XRCC1 polymorphisms and bladder cancer risk." (PMID 23704969, 2013). "Thus, to clarify the effect of XRCC1 variants (Arg194Trp and Arg399Gln) on bladder cancer risk, we performed a meta-analysis of all eligible studies." (PMID 23496911, 2013). "Therefore, we performed a meta-analysis of all available studies to clarify the effects of XRCC1 polymorphisms on bladder cancer risk." (PMID 24039945, 2013). "Thus, it is reasonable to conclude that functional SNPs of XRCC1 are associated with susceptibility to bladder cancer." (PMID 23704969, 2013). "In summary, this is the first meta-analysis investigating the correlation between XRCC1 polymorphisms and bladder cancer risk in Asian and our results suggest that XRCC1 Arg194Trp and Arg280His polymorphisms are associated with increased risk of bladder cancer in Asian population." (PMID 23704969, 2013). "The aim of our study was to clarify the effects of XRCC1 variants on bladder cancer risk." (PMID 23496911, 2013). "However, the XRCC1 R194W and R280H polymorphisms were both associated with increased bladder cancer risk among Asians." (PMID 24039945, 2013). "In addition, several recent genetic association studies based on Asian population revealed significant association of XRCC1 Arg194Trp and Arg280His polymorphisms with bladder cancer risk." (PMID 23704969, 2013). "Subgroup analyses of XRCC1 Arg194Trp and Arg399Gln polymorphisms and bladder cancer risk." (PMID 23704969, 2013). "In conclusion, despite some limitations, the results of our meta-analysis suggest that two polymorphisms in XRCC1 (Arg194Trp and Arg399Gln) may contribute to bladder cancer development." (PMID 23496911, 2013). "Although the sample size of these studies was small, they indicated that the association between XRCC1 polymorphisms and bladder cancer risk in Asian could be different from that in Caucasian." (PMID 23704969, 2013). "Meta-analysis of the XRCC1 gene polymorphisms on bladder cancer risk." (PMID 24039945, 2013). "Hence, to provide the most comprehensive assessment of the associations between the XRCC1 polymorphisms and bladder cancer risk, we performed an updated meta-analysis of all available studies." (PMID 24039945, 2013). "Subsequently, many studies have been published on this controversial issue, but it remains unclear whether there are significant associations between XRCC1 polymorphisms and bladder cancer risk." (PMID 24039945, 2013). "Therefore, it is necessary to perform a quantitative meta-analysis to answer the question whether XRCC1 polymorphisms are associated with bladder cancer risk in Asian." (PMID 23704969, 2013). "However, the XRCC1 R399Q polymorphism may play a protective role against bladder cancer among smokers." (PMID 24039945, 2013).
bladder cancer (continued). "SNP of XRCC1 may increase the risk of some types of cancer by damaging the interaction of XRCC1 with other enzymatic proteins and, consequently, altering DNA repair activity; this may result in carcinogenesis, including a higher incidence of bladder cancer." (PMID 23496911, 2013). "Therefore, large and carefully designed case–control studies need to be performed to provide the best evidence for the possible associations between the XRCC1 R194W and R280H polymorphisms and bladder cancer risk among Asian populations and African populations." (PMID 24039945, 2013). "Hence, it is biologically reasonable to hypothesize a potential relationship between XRCC1 polymorphisms and Bladder cancer risk." (PMID 24039945, 2013). "Thus we performed this meta-analysis to determine whether XRCC1 polymorphisms were associated with susceptibility to bladder cancer in Asian, and this is the first meta-analysis on this topic." (PMID 23704969, 2013). "A serial of studies demonstrate that the onset and progression of bladder cancer are closely associated with multiple gene polymorphisms including CD44, XRCC1, and PDCD6." (PMID 30755233, 2019). "APEX1 rs3136817, MUTYH rs3219493, three SNPs (rs3213356, rs25487 and rs1799782) in XRCC1, and three SNPs (rs1799794, rs861531 and rs861530) in XRCC3 showed significant associations with the risk of bladder cancer." (PMID 27153553, 2016). "Here we aimed to assess the associations of nineteen polymorphisms from seven DNA repair–associated genes (PRAP1, OGG1, APEX1, MUTYH, XRCC1, XRCC2 and XRCC3) with bladder cancer and their interactions in the disease in a Han Chinese population." (PMID 27153553, 2016). "X-ray repair cross-complementing group 1 (XRCC1) is an important DNA repair protein in the base excision repair (BER) pathway and, for decades, it has been known to be associated with bladder cancer." (PMID 25938407, 2015). "We reviewed seven meta-analyses and found that subjects with the XRCC1 Arg194Trp Arg/Trp + Trp/Trp genotype had a 1.2-fold (1.02–1.41) increased OR (95%CI) of bladder cancer compared to those with the Arg/Arg genotype." (PMID 25938407, 2015). "Polymorphisms of x-ray cross complementing group 1 (XRCC1), a gene involved in the DNA base excision repair (BER) pathway, have been suspected with bladder cancer risk for decades." (PMID 23704969, 2013). "However, bladder cancer patients with high XRCC1 expression had a favorable chemosensitivity to platinum-based chemotherapy." (PMID 32426369, 2020). "After screening the titles and abstracts, 63 were excluded (40 did not examine XRCC1 R399Q, R194W and R280H Polymorphisms and bladder cancer risk, 23 were overlapped studies among the three databases) and only 39 full-text publications were preliminarily identified for further detailed evaluation." (PMID 24039945, 2013). "We found none of the 14 XRCC1 polymorphisms was associated with bladder cancer risk." (PMID 17425776, 2007). "Variants in the XRCC1 gene might alter protein structure or function or create alternatively spliced proteins which may influence BER efficiency and hence affect individual susceptibility to bladder cancer." (PMID 17425776, 2007). "The subset of bladder cancer dataset contained 7 SNPs, XRCC3 (rs861539), APE1 (rs3136820), XPD_751 (rs13181), XRCC1_399 (rs25487), XPD_312 (rs1799793), XRCC1_194 (rs1799782), XPC_PAT (rs2228001)." (PMID 27053949, 2016).
hepatocellular carcinoma (18 papers, 2013 to 2024). A malignant tumor that arises from hepatocytes. "Several epidemiological studies have shown a positive correlation between the XRCC1 399Gln polymorphism and colorectal and hepatocellular carcinoma." (PMID 38983993, 2024). "A number of studies reported that XRCC1 polymorphism is associated with different types of cancer including lung, esophageal, breast, bladder, gastrointestinal, as well as hepatocellular carcinoma." (PMID 33171788, 2020). "False-positive report probability values for associations between the risk of hepatocellular carcinoma and the frequency of genotypes of XRCC1 gene." (PMID 30408066, 2018). "On the basis of these observations, our meta‐analytical findings suggested that XRCC1 gene Arg399Gln was another susceptibility locus for hepatocellular carcinoma in Chinese." (PMID 27306318, 2016). "The arginine194tryptophan (Arg194Trp) polymorphism in the X-ray repair cross-complementing group 1 (XRCC1) gene has been reported to be associated with hepatocellular carcinoma (HCC), however, the results from previous studies are conflicting." (PMID 25202399, 2014). "Several previous meta-analyses assessed the association of XRCC1 Arg399Gln polymorphism with risk of breast, lung and hepatocellular cancer, and so on." (PMID 24205095, 2013). "Furthermore, this work analyzes the potential association of these two XRCC1 gene SNPs with further development of complications (cirrhosis and hepatocellular carcinoma) in such patients." (PMID 30366460, 2018). "Taken together, our findings demonstrated that XPD gene Asp312Asn and XRCC1 gene Arg399Gln might be candidate susceptibility loci for hepatocellular carcinoma." (PMID 27306318, 2016). "In conclusion, we through a comprehensive meta‐analysis demonstrated that XPD gene Asp312Asn and XRCC1 gene Arg399Gln might be candidate susceptibility loci for hepatocellular carcinoma." (PMID 27306318, 2016). "However, our results showed that such association was observed just for breast and hepatocellular cancer, suggesting that other factors may be modulating the XRCC1 polymorphism functionality." (PMID 24205095, 2013). "We, therefore, decided to meta‐analytically assess the association of six non‐synonymous coding variants from XRCC1,XRCC3 and XPD genes with hepatocellular carcinoma risk by pooling the results of 20 English articles." (PMID 27306318, 2016). "A study in China showed that XRCC1, XRCC3, XRCC4, XRCC7, XPC and XPD gene polymorphisms in combination with a high exposure to AFB1 (determined by measuring serum AFB1-albumin adduct levels in peripheral blood cells) were associated with an increased risk of developing a hepatocellular carcinoma." (PMID 32542409, 2020). "The aim of this meta-analysis was to assess the prognostic value of XRCC1, XRCC3, and ERCC2 gene polymorphism in hepatocellular carcinoma (HCC)." (PMID 31281357, 2019). "Although the overall association between XRCC1 gene Arg399Gln and hepatocellular carcinoma was negative, further stratified analyses revealed that country, sample size, hepatitis B virus infection and source of controls constituted the potential sources of heterogeneity." (PMID 27306318, 2016). "However, the expression profiles and prognostic values of XRCCs (XRCC1-6) in hepatocellular carcinoma (HCC) have not been explored up to now." (PMID 32258128, 2020).